ERBB2 (erb-b2 receptor tyrosine kinase 2)
Diseases named in the same sentence as ERBB2 in open-access papers (continued):
Sharing a sentence is not in itself a finding about the gene and the disease.
endometrial cancer (175 papers, 2004 to 2026). Primary or metastatic malignant neoplasm involving the endometrium (mucous membrane that lines the endometrial cavity). "Recently the TAPUR study evaluated the efficacy of pertuzumab plus trastuzumab in heavily pretreated patients with endometrial cancer with ERBB2/3 amplification, overexpression, or mutation." (PMID 40862761, 2025). "A subset of CNH endometrial cancer characterized by amplification in ERBB2 (commonly referred to as HER2 gene), is associated with poor outcomes." (PMID 41340866, 2025). "Another widely studied therapeutic target for endometrial cancer is human epidermal growth factor receptor 2 (HER2), a receptor tyrosine-protein kinase encoded by ERBB2." (PMID 38791945, 2024). "The two patients who had a PR in the ERBB2 mutation subgroup received a combination of paclitaxel, trastuzumab and everolimus for an adenocarcinoma of cervix and an endometrial carcinoma, both harboring ERBB2 S310Y mutation." (PMID 29515767, 2018). "Through this classification we and others have reported that USC has a higher proportion of ERBB2 amplifications (i.e., 27–44%) compared to other endometrial cancer subtypes." (PMID 40862761, 2025). "The drug is currently being evaluated in clinical trials for its efficacy in endometrial cancer, particularly in ERBB2-positive patients." (PMID 40046734, 2025). "Anti-HER2 therapy is indicated for erb-b2 receptor tyrosine kinase 2 (ERBB2)-amplified/overexpressing endometrial carcinoma (EC)." (PMID 39031567, 2024). "The transmembrane receptor human epidermal growth factor receptor 2 (HER-2/neu), which is encoded by the ERBB2 gene, also has promise for the treatment of endometrial cancer." (PMID 37511876, 2023). "Collectively, our data indicate not only that ERBB2R678Q is one of the most frequent ERBB2 mutations in cancer globally, but also indicate for the first time that ERBB2R678Q is particularly enriched in endometrial cancer." (PMID 36373729, 2022). "Previously, we used the TCGA database for gene expression profiling of breast, ovary, and endometrial cancers, and identified a top-scoring network centered on the ERBB2 gene, which plays a crucial role in carcinogenesis in the three estrogen-dependent tumors." (PMID 35740327, 2022). "Some of these genes, such as CDKN2A, E2F1, and ERBB2, have been characterized in endometrial cancer tumorigenesis." (PMID 35205261, 2022). "We constructed a prognostic model of endometrial cancer containing four risk ARGs (CDKN2A, PTK6, ERBB2, and BIRC5) using multivariate and univariate Cox, and LASSO regression analyses." (PMID 33109128, 2020). "In summary, by collecting and analyzing the transcript information of endometrial cancer samples from TCGA database, we identified four prognosis-associated autophagy genes (CDKN2A, PTK6, ERBB2, and BIRC5)." (PMID 33109128, 2020). "In endometrial cancer, three differentially expressed ARGs (ERBB2, BAK1 and MYC), which are closely related to the occurrence of endometrial cancer, were increased." (PMID 33109128, 2020).
endometrial cancer (continued). "In particular, miR-125b down-regulation correlated with endometrial cancer invasion by targeting the proto-oncogene ERBB2 and inducing proliferation, colony formation, migration and invasion of cutaneous squamous cell carcinoma cells." (PMID 30682201, 2019). "For example, the Erb-B2 Receptor Tyrosine Kinase 2 (HER2) is overexpressed in subsets of breast, ovarian, gastric, colorectal, pancreatic and endometrial cancers." (PMID 30214377, 2018). "In our study, although ErbB-2 was upregulated in endometrial cancer, ErbB-2 and ErbB-3 were downregulated in patients with vulvar cancer." (PMID 26559525, 2015). "Finally, the identification of c-erbB2 as the most highly differentially expressed gene in USPC suggest that targeting HER-2/neu by rhuMAb anti-HER-2 (Herceptin) may be potentially highly beneficial against these biologically aggressive and chemotherapy-resistant variants of endometrial cancer." (PMID 15208622, 2004). "By achieving a median PFS of 16 weeks and a median OS of 61 weeks across all patients, the study demonstrated that the combination of pertuzumab and trastuzumab exhibits antitumor activity in heavily pretreated patients with endometrial cancer harboring ERBB2/3 amplification." (PMID 40862761, 2025). "Notably, MECOM amplification co-occurred with CCNE1 and ERBB2, two subsets of endometrial cancer known for their poor prognosis in CNH tumors." (PMID 41340866, 2025). "The epidermal growth factor receptor 2 (ERBB2, formerly HER2)–targeting antibody drug conjugates (vic-)trastuzumab duocarmazine and trastuzumab deruxtecan have recently been tested in endometrial cancer (EC), including patients with ERBB2 immunohistochemistry score 1+ and 2+–expressing tumors." (PMID 39235791, 2024). "It has been shown that the gene amplification of HER2 (ERBB2) and overexpression of EGFR (ERBB1) are respectively associated with aggressive types (papillary serous and clear cell histologies) and a poor survival rate among patients with endometrial cancer." (PMID 26849234, 2016). "Indeed, endometrial serous carcinoma has been found as the histology showing the highest frequency of ERBB2 amplification, up to 38%, followed by other subtypes likewise clear cell or endometrioid carcinoma as pointed out by a study evaluating 2042 endometrial carcinomas." (PMID 36010253, 2022). "Immunohistochemistry revealed ISH scores for four risk ARGs (CDKN2A, ERBB2, PTK6, and BRIC5) were significantly higher in endometrial cancer tissue than in healthy endometrial tissue, which suggested that these genes are highly expressed in endometrial cancer tissues." (PMID 33109128, 2020). "For example, endometrial cancer is characterized by intrachromosomal amplification of ESR1, KRAS, PIK3CA, ERBB2, TERC, MYC, CCNE1." (PMID 41415205, 2025). "Despite these limitations, this study leverages a large, well-characterized cohort with comprehensive genomic profiling, enabling detailed evaluation of CNH endometrial cancers and MECOM, CCNE1, and ERBB2 gene amplifications." (PMID 41340866, 2025). "The objective of this study was to characterize a novel subset of CNH endometrial cancer, MECOM amplified, and to examine the overlap of MECOM amplification with amplification in CCNE1 and ERBB2 using a publicly available dataset." (PMID 41340866, 2025). "ERBB2 was amplified in 5.2 % (27/523) of tumors in the cohort, and in the subset of ERBB2 amplified tumors, 92.6 % (25/26) were found in CNH endometrial cancer." (PMID 41340866, 2025).
endometrial cancer (continued). "Human epidermal growth factor receptor 2 (HER2)/erythroblastic oncogene B 2 (ERBB2) is often overexpressed in breast, gastric, esophageal, ovarian, and endometrial cancers." (PMID 38221520, 2024). "Among these, lapatinib, a dual inhibitor targeting both HER2 (ErbB2) and EGFR (ErbB1), has been extensively studied for its efficacy in many cancer types, including endometrial carcinoma." (PMID 39768892, 2024). "Among 92 endometrial carcinomas analyzed by NGS and HER2 IHC-FISH, 10 (10.9%) had ERBB2 gene amplification by NGS, all of which were HER2-positive by IHC-FISH." (PMID 38893219, 2024). "In the present study, using a TCGA dataset, we found that ERBB2 and ERBB3 were overexpressed in breast and endometrial cancer tissues compared with normal counterparts." (PMID 35740327, 2022). "Four ARGs (CDKN2A, PTK6, ERBB2 and BIRC5) were selected to establish a prognostic model of endometrial cancer." (PMID 33109128, 2020). "Our prognostic model assessing four ARGs (CDKN2A, PTK6, ERBB2, and BIRC5) suggested their potential as independent predictive biomarkers and therapeutic targets for endometrial cancer." (PMID 33109128, 2020). "Immunohistochemistry suggested that among the four ARGs the protein levels of CDKN2A, PTK6, ERBB2, and BIRC5 were higher in endometrial cancer than healthy endometrial tissue." (PMID 33109128, 2020). "Furthermore, even in the absence of co-amplification of CCNE1 or ERBB2, MECOM amplification alone conferred a similar two-fold increase in risk, suggesting that MECOM amplification may independently identify an aggressive subset of endometrial cancers." (PMID 41340866, 2025).
glioma (174 papers, 2007 to 2026). A benign or malignant brain and spinal cord tumor that arises from glial cells (astrocytes, oligodendrocytes, ependymal cells). "The remaining genes Erbb2, Kras and Tert, and Braf and Idh1, contained variants in five and two gliomas, respectively." (PMID 38232086, 2024). "High serum ErbB2 concentration was also associated with glioma risk overall (P = 0.049; OR = 1.39, 95 % CI = 1.00–1.93)." (PMID 26906551, 2016). "We assessed the associations between genetic glioma risk variants and serum concentrations of EGFR and ErbB2, as measured in pre-diagnostic cohort serum samples of 593 glioma patients and 590 matched cancer-free controls." (PMID 26906551, 2016). "Some genes in this survival module were similarly implicated in the occurrence and development of glioma, such as ERBB2, ITGB3, EGFR, and MET." (PMID 24809850, 2014). "Similar to our findings in Nf2-deficient SC NPCs, ErbB2 increases glioma cell growth by inhibiting apoptosis." (PMID 24817309, 2014). "High serum concentration of ErbB2 was also associated with glioma risk overall." (PMID 26906551, 2016). "In addition, ErbB2 is one of the most frequently mutated genes in human high-grade glioma, such that ErbB2 activation promotes glioma and ependymoma cell line growth in vitro." (PMID 24817309, 2014). "The BiME simultaneously targets ErbB2 on glioma cells and CD206 on M2 macrophages, reprogramming macrophages toward pro-inflammatory M1 phenotype while promoting macrophage-tumor cell bridging, enhancing tumor cell phagocytosis and antigen presentation." (PMID 41965349, 2026). "Positive outcomes were also seen in a murine orthotopic model for brain stem gliomas, produced from patient-derived brainstem glioma cells using with ErbB2 CAR PBAE complexes administered using convection enhanced delivery." (PMID 41438289, 2026). "ERBB2 fusion alone was found in patients with lung, colorectal, gastric, glioma, ovarian, endometrial, and gastrointestinal stromal tumors." (PMID 36276102, 2022). "Inhibition of ERBB receptors can lead to suppression of cancer cell migration and inhibition of NRG1/ERBB2 signaling reduces migration of human glioma cells." (PMID 36239094, 2022). "The study identified eight co-downregulated miRNAs, three co-upregulated miRNAs, and seven genes associated with overall glioma survival, namely, KRAS, IFNB1, ALCAM, ERBB2, STAT3, FOSL1, and EN2." (PMID 36061185, 2022). "In summary, the mRNA levels of EGFR and ERBB2 were higher in advanced and poorly differentiated gliomas; however, the mRNA levels of ERBB3 and ERBB4 were lower in advanced and poorly differentiated gliomas." (PMID 33892666, 2021). "In the TCGA data, the expression level of ERBB2 in IDH wild-type gliomas was notably increased, and it was also increased in the CGGA RNA-seq datasets." (PMID 33892666, 2021). "EGFR and ERBB2 were notably downregulated in IDH mutant gliomas, while ERBB3 and ERBB4 were upregulated, which was associated with a poor prognosis." (PMID 33892666, 2021). "ERBB2 mRNA expression was notably positively correlated with the level of macrophage infiltration in gliomas (r = 0.1026, p = 0.0072)." (PMID 33892666, 2021). "Exosomes derived from the peripheral blood samples of human glioma patients are reported to carry GBM-specific gDNA of ERBB2, CDK4, AKT3, MDM2, and RB1 genes." (PMID 33137926, 2020). "We treated glioma cells with an irreversible dual EGFR/ErbB2 inhibitor (afatinib) to evaluate the effects of the EGFR and ErbB2 pathways on DSE-regulated malignant phenotypes." (PMID 29864158, 2018). "Most strikingly, the expression of EGFR and ERBB2—two commonly targeted RTKs in the treatment of glioma—was much higher in adult GBM compared to pHGG and DIPG." (PMID 29164272, 2018). "The protein expression of the different EGFR family members was predominantly seen in tumor cells in both glioma and meningioma, except for ErbB2." (PMID 27091344, 2016).
glioma (continued). "We investigated associations between pre-diagnostic serum protein concentrations of EGFR and ErbB2, both members of the EGFR family, and future risk of glioma." (PMID 26906551, 2016). "RMPAhigh gliomas were also enriched in the expression of ERBB2, FGFR1 and MET (and its ligand HGF), DDR2 (a receptor for activated collagen fibers), as well as the WNT co-receptors ROR1 and RYK." (PMID 27385209, 2016). "This missing information offered a compelling rationale for our study: we investigated potential associations between known glioma risk variants and pre-diagnostic serum levels of EGFR and ErbB2." (PMID 26906551, 2016). "Numerous studies have found an association between the expression of EGFR and its heterodimerization partner ErbB2 within different tumors, including gliomas." (PMID 26906551, 2016). "In this study, we investigated if there is a correlation between genetic glioma risk variants and levels of EGFR and ErbB2 in pre-diagnostic sera from glioma patients and matched controls." (PMID 26906551, 2016). "Especially ERBB2, being the dimerization partner of EGFR, has previously been associated with glioma risk." (PMID 25537509, 2015). "In 2008, Contessa and colleagues reported that inhibition of N-linked glycosylation reduced RTK (i.e. EGFR, ErbB2, ErbB3 and IGF-IR) signaling through AKT and radiosensitized tumor cells in glioma and pancreatic adenocarcinoma cell lines." (PMID 22192458, 2011). "Five out of the ten top hub nodes from general glioma networks from StringDB and BioGRID are matching genes containing erb-b2 receptor tyrosine kinase 2 (HER2), erb-b2 receptor tyrosine kinase 4 (HER4), cyclin D3 (CCND3), TEK tyrosine kinase (TEK), and transforming growth factor alpha (TGFA)." (PMID 31952211, 2020). "Although we cannot exclude that other pathways may involve in DSE-mediated phenotypes, blocking EGFR/ErbB2 signaling by afatinib can inhibit DSE-induced malignant phenotypes in glioma cells." (PMID 29864158, 2018). "Several genes are associated with CpG sites that drastically differ in methylation, shown in dark blue (unmethylated) and dark red (methylated), among them, ERBB2, a member of the epidermal growth factor (EGF) family and known to be associated with glioma susceptibility." (PMID 28768481, 2017). "Further, we studied if EGFR glioma risk variants were associated with EGFR and ErbB2 serum levels." (PMID 26906551, 2016). "EGFR family members (EGFR, ErbB2–4) have been evaluated concomitantly in glioma and meningioma." (PMID 27091344, 2016). "We first analyzed levels of Met and ErbB2 in our collection of glioma cell lines by Western blot." (PMID 25762646, 2015). "EGFR-KDD is most prevalent in glioma and NSCLC, while ERBB2-KDD is most prevalent in breast and gynecological cancers (GYN)." (PMID 33654076, 2021). "Cdk4 is required for ErbB-2-driven mammary tumorigenesis, DMBA/TPA-induced skin tumor development, Men1+/−-driven neuroendocrine tumorigenesis, PDGF-induced glioma and APCMin/+-driven adenoma." (PMID 33806417, 2021). "In this study, 47.6% of glioma patients were detected ctDNA including 1p/19q, MDM2, ERBB2, IDH1, CDKN2A, CDK4, PDGFRA, CCNE1, MET." (PMID 32973641, 2020). "Concomitantly, the mean EGFR, ERBB2, FGFR3, and PDGFRB mRNA levels were statistically lower than those of IDH-wildtype gliomas, which also exhibited a marked increase in EGFR and ERBB2 protein abundance." (PMID 27852048, 2017). "We observed increased DNA methylation in EGFR, ERBB2, ERBB3, FGFR3, and PDGFRB in IDH-mutant gliomas as the mean methylation of each gene was statistically greater than that of IDH-wildtype." (PMID 27852048, 2017).
glioma (continued). "In addition, we evaluated the association between the risk for glioma and pre-diagnostic serum levels of EGFR and ErbB2 using both dichotomized and continuous protein abundance data to understand if chronic activation and high levels of the receptors could be a mechanism in gliomagenesis." (PMID 26906551, 2016). "Several genes including e.g. F5, LAMA1, ERBB2 or STARD3 seems to be in proximity to genes of the EGF/EGFR signaling cascade, which is known to be important in glioma." (PMID 25537509, 2015). "According the previous results, ERBB-2 and ERBB-3 mRNAs were detected only in a few high-grade gliomas, while ERBB-4 expression was most pronounced in low-grade gliomas." (PMID 24986561, 2014). "Glioma-related ctDNAs included 1p/19q, MDM2, ERBB2, IDH1, CDKN2A, CDK4, PDGFRA, CCNE1, MET." (PMID 32973641, 2020). "Moreover, the ctDNAs in the metastatic brain tumors included ALK and MDM2, and glioma-related ctDNAs included 1p/19q and MDM2 followed by frequencies of ERBB2, IDH1, CDKN2A, CDK4, PDGFRA, CCNE1, MET." (PMID 32973641, 2020). "Aberrant phosphotyrosine-based signaling is a hallmark of cancer, and gliomas are no exception; tyrosine kinase membrane receptors like EGFR, ERBB2, PDGFRA, MET and VEGFR2 have been implicated in glioma growth, angiogenesis and cell motility." (PMID 25238264, 2014). "Immunofluorescence analysis showed that ERBB2 was clearly expressed in the cytoplasm and cell membrane of human epidermal squamous cell carcinoma A-431 cells, human osteosarcoma U2OS cells, and human glioma U251-MG cells, indicating that ERBB2 expression was not limited to specific cell lines." (PMID 37324014, 2023). "Therefore, we conclude that increased ERBB3 abundance and PIK3R1 expression and decreased ERBB2, FGFR3, and AKT2 expression may explain the improved LGG patient survival in IDH-mutant gliomas compared with IDH-wildtype gliomas." (PMID 27852048, 2017). "Met was strongly detected in all ATCC glioma cell lines, but only in one GSC line, SD02, whereas ErbB2 was only weakly detected in glioma cell lines (data not shown)." (PMID 25762646, 2015).